NLRP3 (NLR family pyrin domain containing 3)
Diseases named in the same sentence as NLRP3 in open-access papers (continued):
Sharing a sentence is not in itself a finding about the gene and the disease.
Hepatic steatosis (continued). "Overall, our findings provide insight into the mechanism by which PcP extracts alleviate hepatic steatosis, highlighting the potential significance of modulating the NLRP3/Caspase‐1/GSDMD pathway in the context of pyroptosis." (PMID 39055201, 2024). "ROS is considered a common signal for NLRP3 inflammasome activation, playing a significant role in the onset and progression of hepatic steatosis and NASH." (PMID 39022762, 2024). "Genetic modifications or pharmacological inhibitors of the NLRP3 inflammasome alleviate HFD-induced hepatic steatosis, hepatocyte inflammation, and fibrogenesis." (PMID 38543036, 2024). "Although the mean relative gene expression level of NLRP3 in patients with mild hepatic steatosis (5.45 ± 2.77) was lower than those with advanced hepatic steatosis (6.01 ± 2.76), this difference didn’t reached a significant level, (p = 0.373) as shown in." (PMID 39179677, 2024). "Uric acid can trigger NLRP3 inflammasome activation, thereby regulating hepatic steatosis and insulin resistance." (PMID 39022762, 2024). "Accumulating evidence indicates that the NLRP3 inflammasome signaling pathway is involved in the progression of hepatic steatosis to NASH through SIRT1." (PMID 38543036, 2024). "A recent study documented that hyperhomocysteinemia promoted Mdm2-mediated ubiquitination of HSF1 to activate hepatic NLRP3 inflammasome, thus leading to hepatic steatosis." (PMID 39277582, 2024). "The results demonstrated that the administration of PcP extract effectively decreased dyslipidemia and hepatic steatosis, which coincided with a decrease in hepatic pyroptosis through modulation of the NLRP3/Caspase‐1/GSDMD pathway in liver tissues." (PMID 39055201, 2024). "Lastly, Galectin-3 is thought to promote hepatic inflammation in fatty liver disease via TLR-4-mediated NLRP3 inflammasome activation." (PMID 39635525, 2024). "The present study demonstrates that atorvastatin reduces hepatic steatosis, inflammation and fibrosis and prevents cholesterol crystal formation, thereby precluding NLRP3 inflammasome activation." (PMID 37175538, 2023). "Correspondingly, our previous study has shown that uric acid regulates hepatic steatosis and impairs insulin sensitivity through activating the NLRP3 inflammasome both in vivo and in vitro." (PMID 36814289, 2023). "Another study showed that MG inhibited hepatic steatosis-induced NLRP3 inflammasome activation through the restoration of autophagy to promote Heme Oxygenase-1 (HO-1) signalling." (PMID 36016562, 2022). "The histological evidence of hepatic steatosis from 9-month-old DIO Nlrp3- mice suggests that compared to WT mice, the ablation of NLRP3 resulted in reduction in hepatic steatosis." (PMID 35432210, 2022). "This leads to the abnormal activation of NLRP3 and thus leads to liver steatosis and inflammatory damage." (PMID 36079844, 2022). "The knockdown of hepatic PINK1 canceled the mitophagy-inducing effect of C3G, which blunted the useful effects of C3G on oxidative stress, NLRP3 inflammasome activation, glucose metabolism, and hepatic steatosis." (PMID 36016562, 2022). "Uric acid can directly induce hepatocyte fat accumulation and hepatic steatosis via the NLRP3 inflammasome." (PMID 35350750, 2022). "Another study using NLRP3−/−, ASC−/−, and caspase-1−/− mice also found that hepatic steatosis and inflammation in NASH were indeed associated with activation of the NLRP3 inflammasome." (PMID 36016562, 2022). "The blockage of NLRP3 inflammasome or caspase-1 alleviated liver steatosis, inflammation, and fibrosis in NAFLD." (PMID 35078487, 2022). "A previous study showed that CBD alleviated hepatic steatosis and oxidative stress and significantly decreased the expression of NF-κB, NLRP3, ASC, procaspase-1, caspase-1 p20, GSDMD, and cleaved GSDMD both in vivo and in vitro." (PMID 36016562, 2022). "We demonstrated that JLD significantly reduced the HFD-induced liver steatosis and suppressed NLRP3 production in vivo." (PMID 35138995, 2022).
Hepatic steatosis (continued). "In this study, our data indicate that RYR ameliorates HFD-induced hepatic steatosis and inflammation by inhibiting NF-κB/NLRP3 inflammasome signaling and SREBP pathways in vivo and in vitro." (PMID 35078487, 2022). "NLRP3 inflammasome activation correlated with liver steatosis, inflammation, fibrosis, and tumorigenesis." (PMID 35078487, 2022). "An excessive uric acid level can directly induce hepatic steatosis through NOD-like receptor family pyrin domain containing 3 (NLRP3) inflammasome-dependent mechanism." (PMID 35250880, 2022). "NLRP3 inflammasomes are critical for the initiation of liver inflammation and the progression from hepatic steatosis to NASH." (PMID 34393826, 2021). "Uric acid stimulates hepatic steatosis either directly or by activating NLRP3 inflammasomes (Lanaspa et␣al, 2012; Wan et␣al, 2016)." (PMID 34694070, 2021). "All in all, these results strongly support that the primary targets of the NLRP3 blockade are liver inflammation and fibrosis, with a mild effect on hepatic steatosis in MCD-fed ApoE-/- mice." (PMID 34513923, 2021). "NLRP3 inflammasome is crucial for the initiation of hepatic inflammatory response and the progression from hepatic steatosis to NASH." (PMID 34393826, 2021). "Taken together, these data suggest that activation of the NLRP3 inflammasome can aggravate hepatic steatosis." (PMID 34956171, 2021). "A recent study showed that oral sulforaphane alleviated hepatic steatosis in mice with a long-term high-fat diet by suppressing inflammatory signals in NLRP3." (PMID 34276585, 2021). "This role of NLRP3 has been documented in HFD-fed rodents, which exhibited decreased liver steatosis by inhibition of the NLRP3 inflammasome pathway." (PMID 35053205, 2021). "Accordingly, the inhibition of NLRP3 inflammasome by related gene knockout or specific inhibitors has been proposed as an effective therapeutic option for fatty liver disease." (PMID 34956171, 2021). "In conclusion, MG inhibited hepatic steatosis-induced NLRP3 inflammasome activation through the restoration of autophagy to promote HO-1 signaling capable of ameliorating oxidative stress and inflammatory responses." (PMID 32992548, 2020). "Subsequent experiments focused on the effects of MGIG intervention on the levels of proteins of the TLR4/NF‐κB/Nlrp3 signalling pathway in HFD‐induced hepatic steatosis." (PMID 32410294, 2020). "Overt activation of NLRP3 inflammasome exacerbated hepatic steatosis, whereas defective inflammasome activation exhibited significant improvement of hepatocyte steatosis, inflammation, and fibrogenesis." (PMID 32992548, 2020). "It was also discovered that hepatic steatosis and inflammation were ameliorated with treatment of apigenin via regulation of the XO/NLRP3 pathways." (PMID 32148553, 2020). "In the in vivo experiments, excessive hepatic steatosis with increased NLRP3 inflammasome and its complex expression were found in adiponectin-KO mice compared to wild-type mice." (PMID 33251225, 2020). "A recent study showed that NLRP3 inflammasome activation is needed for the development of hepatic steatosis, where Nlrp3−/− mice were protected against hepatomegaly, liver injuries, and infiltration of activated macrophages in a long-term manner." (PMID 31998283, 2019). "Caspases 1/11−/− mice presented a more significant presence of liver steatosis compared to both WT and Nlrp3−/− mice." (PMID 31998283, 2019). "XIAP suppresses the assembly of NLRP3 inflammasomes by negatively regulating NLRP3 signaling, reducing the formation and release of inflammatory cytokines, and moderating hepatic steatosis." (PMID 31841118, 2019). "In our model, Nlrp3−/− mice showed increased liver steatosis, macrophage infiltration and liver injury (NAS score)." (PMID 28939830, 2017). "Nevertheless, our results suggest that dietary PUFAs attenuated hepatic NLRP3 inflammasome activation, which in part explains the reduced hepatic steatosis in mice fed dietary PUFAs." (PMID 28729463, 2017).
Hepatic steatosis (continued). "Collectively, our results demonstrate that SFN prevents HFD-induced hepatic steatosis mediated by the suppression of NLRP3 inflammasome activation in hepatocytes." (PMID 27075683, 2016). "More recently, it was revealed that uric acid regulated hepatic steatosis through the NLRP3 inflammasome-dependent mechanism." (PMID 27382573, 2016). "Lipotoxic levels of the saturated fatty acid, palmitate, activate NLRP3, and, accordingly, NLRP3 knockout mice are protected against accumulation of fatty acids in the liver and development of hepatic steatosis." (PMID 26751474, 2016). "Collectively, our results demonstrate that SFN prevents HFD-induced hepatic steatosis mediated by the suppression of NLRP3 inflammasome activation in the liver." (PMID 27075683, 2016). "Elevated uric acid levels promote hepatic steatosis by activating the NLRP3 inflammasome, while AST, reflecting mitochondrial dysfunction and hepatocyte injury, showed a positive association with SAF (β = 0.003), supporting its role as a marker of disease activity." (PMID 40224639, 2025). "Given that the NLRP3 inflammasome contributes to hepatocyte lipid metabolism disorders 27, we next examined whether inhibiting NLRP3 with Cas9/gNLRP3@M-N could attenuate hepatic steatosis in GAN diet-fed mice." (PMID 40521185, 2025). "Furthermore, it inhibits ferroptosis through the SIRT1/Nrf2 pathway, improving fatty liver disease, and blocks NLRP3-Caspase-1-GSDMD-mediated pyroptosis in H9C2 and RAW264.7 cells." (PMID 40391374, 2025). "Similarly, NLRP3-, CASP1-, and ASC-deficient mice consuming a methionine-/choline-deficient diet (MCDD) showed elevated serum transaminases and exacerbated liver steatosis compared to wild-type mice." (PMID 39770566, 2024). "Interestingly, Nlrp3−/− mice fed HFD are more insulin and glucose sensitive, and protected from hepatic steatosis, compared with Nlrp3 sufficient controls." (PMID 36994095, 2023). "Fortunately, DAU could alleviate alcohol−induced liver inflammation induced by regulating p38/NF−κB/NLRP3 pathway, and it also has significant effects on hepatic steatosis and oxidative stress in the liver." (PMID 36615880, 2023). "Moreover, TGR5 agonists increase the phosphorylation of PKA and induce ubiquitination of NLRP3 inflammasome, which inhibits NLRP3-mediated M1 macrophage polarization, thereby alleviating liver steatosis and inflammation in NASH." (PMID 37570840, 2023). "Nevertheless, the role of uric acid in hepatic steatosis and IR through NLRP3 inflammasome activation has already been described, and compounds targeting serum uric acid levels have been proposed as therapeutic approaches for nonalcoholic fatty liver disease treatment." (PMID 37599368, 2023). "An n-6 PUFA–enriched high-fat diet induced hepatic steatosis and fibrosis, along with the activation of the NLRP3 inflammasome, in mice, whereas the inhibition of n-6 PUFA metabolites reduced pro-inflammatory factor secretion and inhibited NLRP3 inflammasome activation." (PMID 35571243, 2022). "However, the effect of SIRT6 on regulating the NLRP3 inflammasome in hepatic steatosis progression remains elusive." (PMID 36558977, 2022). "Furthermore, the excessive ROS production can activate NLRP3-mediated inflammation, strengthening the generation of inflammatory cytokines and ultimately promoting the progression of simple fatty liver to NASH." (PMID 35800450, 2022). "Another NASH study suggested that a Chinese herbal formula reduced hepatic steatosis maybe through decreasing certain gut bacteria (such as Verrucomicrobiaceae), alleviating intestinal endotoxemia, and reducing NLRP3 inflammasome activation." (PMID 35784533, 2022). "Besides, NLRP3 plays a key role in the pathogenesis of hepatic steatosis suggesting a link between chronic inflammation and lipid accumulation in the liver." (PMID 36376416, 2022).
Hepatic steatosis (continued). "It was also found that T3 may ameliorate the inflammatory response and progression of cirrhosis in mice with alcoholic fatty liver by negatively regulating the NLRP3 signaling pathway." (PMID 36503486, 2022). "Recently, experimental research revealed the mechanism underlying Dansheng Zexie decoction in treating NAFLD, which reduces lipid accumulation and alleviates hepatic steatosis, oxidative stress, and inflammation via inhibiting the ROS/NLRP3/IL-1β signaling pathway." (PMID 36160411, 2022). "Finally, CypA inhibitor TMN355 attenuated liver steatosis and injury and inhibited NF-κB/NLRP3 signaling pathway." (PMID 32903542, 2020). "In contrast, overexpression of XIAP by transfection in vitro restrained PA-stimulated hepatic steatosis by suppression of oxidative stress, NLRP3 related inflammatory response, and impairment of Nrf2 activity, further alleviating abnormal metabolic disorder associated NAFLD." (PMID 31841118, 2019). "HFD-induced liver steatosis in WT mice was also verified biochemically with markedly elevated hepatic levels of cholesterol and TG, and importantly, Nlrp3−/− and Asc−/− (Pycard−/−) livers showed significantly reduced levels of these lipid components in response to HFD feeding compared with WT mice." (PMID 31379826, 2019). "Although HFD groups of WT and NLRP3−/− mice showed similar grades of liver steatosis, hepatocyte ballooning and inflammatory cell infiltration were markedly attenuated in the MCD-fed group of NLRP3−/− mice (II vs I, arrows, hepatocyte ballooning and inflammatory cells, arrowhead, normal area)." (PMID 28499273, 2017). "Multiple studies using mice deficient in different components of the NLRP3 inflammasome (NLRP3 and caspase-1) have consistently shown that loss of the NLRP3 inflammasome decreases HFD-induced hepatic steatosis and inflammation and improves systemic insulin sensitivity." (PMID 24795720, 2014). "Additionally, it has been suggested that GGQLD could potentially alleviate non-alcoholic fatty liver disease (NAFLD) and hepatic steatosis by regulating inflammatory factors and oxidative stress through modulation of the NLRP3 signal axis." (PMID 37370132, 2023). "Also, plenty of studies suggest that NLRP3 is harmful to hepatic steatosis and NASH pathogenesis." (PMID 33273997, 2019). "In conclusion, these result suggested that the Chinese herbal formula HJF reduced hepatic steatosis maybe through decreasing certain gut bacteria (such as Enterobacteriaceae bacteria and F. rappini), alleviating intestinal endotoxemia and reducing NLRP3 inflammasome activation." (PMID 29675053, 2018). "In addition, we also found that treatment with TR could suppress hepatic steatosis in diabetic mice, suggesting that inhibition of NLRP3 inflammasome with TR can improve the dysfunction of both glucose and lipid metabolism." (PMID 29531021, 2018). "Our findings reveal that RES ameliorates fatty liver injury primarily by inhibiting the NLRP3 inflammasome through PINK1-mediated mitophagy, which provides a potential novel therapeutic strategy for mitigating fatty liver disease." (PMID 41976001, 2026). "There is a strong correlation between NLRP3 and the progression of fatty liver, and DAPA is a specific inhibitor of NLRP3." (PMID 40136402, 2025). "Building on prior research, our study demonstrated that Nlrp3−/− mice exhibit increased hepatic injury, characterized by elevated plasma ALT and AST levels, along with enhanced liver steatosis and lipid expression." (PMID 39605303, 2024). "To further explore the mechanism of YCWLP regulation of hepatic steatosis, we detected the expression of related proteins in the SHP2/PI3K/NLRP3 pathway in HepG2 cells." (PMID 39101141, 2024). "Activation of FFA4 by n-3 PUFAs inhibited hepatic steatosis, liver injury, expression of lipogenic SREBP-1c in alcohol-treated mice, and expression of Tnf-α, Cox-2, and Nlrp3 in Kupffer cells." (PMID 38791514, 2024).
Hepatic steatosis (continued). "It has been documented that a small-molecule NLRP3 inhibitor, MCC950, reduced liver inflammation and fibrosis in experimental mice with fatty liver diseases." (PMID 36058909, 2022). "Taken together, the present study helped to elucidate how HFD-induced hepatic steatosis was regulated by XIAP, possibly via the inhibition of NLRP3 signaling and oxidative stress injury." (PMID 31841118, 2019). "In conclusion, we demonstrated that the TCM formula HJF reduces hepatic steatosis, and this effect could be by decreasing certain gut bacteria (such as Enterobacteriaceae bacteria and F. rappini), alleviating intestinal endotoxemia and reducing activation of the NLRP3 inflammasome." (PMID 29675053, 2018). "NLRP3 inflammasome activation can lead to NAFLD development and progression, including hepatic steatosis, inflammation, liver injury, and fibrogenesis." (PMID 27446858, 2016). "The effects were pronounced in wild-type (WT) mice, while NLRP3 −/− mice exhibited less hepatic steatosis than WT mice; however, NAR did not further reduce hepatic steatosis in the NLRP3 −/− group." (PMID 40867875, 2025). "TAX is able to ameliorate alcohol-related liver steatosis via P2X7R and NLRP3 suppression in mice." (PMID 38674122, 2024). "NLRP3 > 7.17 demonstrated 32.58 sensitivity and 80.65% specificity in distinguishing between early and advanced hepatic steatosis, but with a non-significant p value." (PMID 39179677, 2024). "For instance, mice lacking the NLRP3 gene and fed a high-fat diet exhibited worsened liver steatosis, increased macrophage infiltration, and heightened liver injury." (PMID 39770566, 2024). "The results showed that ACT001 reduced serum lipid and inflammatory factor levels, attenuated hepatic steatosis, inflammation and fibrosis, and inhibited hepatic oxidative stress and activation of NOD-like receptor protein 3 (NLRP3) inflammatory vesicles in NASH mice." (PMID 37443174, 2023). "In summary, SA could inhibit the activation of NLRP3 in NASH rats to improve hepatomegaly, inflammation, and hepatic steatosis." (PMID 38026986, 2023). "A different, recently described Nlrp3-specific inhibitor called CY-09 injected daily intraperitoneally in WT mice on a high-fat diet for 14 weeks resulted in less weight gain and hepatic steatosis (hepatic inflammation and fibrosis were not reported)." (PMID 36641116, 2023). "Research studies conducted in the NLRP3 murine model have demonstrated that deleting NLRP3 augments WAT browning, lipolysis, hepatic steatosis and impairs wound healing, suggesting that inflammatory mediators have beneficial effects in the acute phase post-burn." (PMID 33251224, 2020). "Thus, they discovered that TAX was able to reduce lipid accumulation and steatosis via P2X7R and NLRP3 suppression in mice with ALD, paving the way for NFLRP3-P2X7R regulation as a potential therapeutic target for alcohol-related liver steatosis, although further research is needed." (PMID 38674122, 2024). "Therefore, the components of OSA-derived exosomes may increase the level of NLRP3 inflammasomes by inhibiting the SIRT3/AMPK pathway in macrophages, thereby promoting M1 polarization and liver steatosis." (PMID 38764033, 2024). "In another recent study, administration of a different Nlrp3 inhibitor called IFM-514 via intra-peritoneal injection (100 mg/kg) daily, 5 days/week for 4 weeks to ApoE−/− mice on a MCD diet was also found to reduce hepatic steatosis, inflammation, and fibrosis." (PMID 36641116, 2023). "In NAFLD patients who have fatty liver but no inflammation, the expression of NLRP3 components is increased, but the inflammasome is not activated; however, in patients with fatty liver and inflammation, the NLRP3 inflammasome complex is assembled and functional." (PMID 34203484, 2021). "Moreover, the activation of NLRP3 inflammasome might lead to the NAFLD development and progression, including hepatic steatosis, liver injury, and fibrogenesis." (PMID 31485221, 2019).